MITF (melanocyte inducing transcription factor)
Diseases named in the same sentence as MITF in open-access papers (continued):
Sharing a sentence is not in itself a finding about the gene and the disease.
skin pigmentation disorder (4 papers, 2020 to 2024). A pigmentation disease that involves the zone of skin. "From these findings, MITF has become a potential therapeutic target for skin pigmentation disorders or whitening." (PMID 32034251, 2020). "This suppression of MITF activity consequently leads to reduced melanin production, highlighting the potential of DTA as a novel therapeutic agent for skin pigmentation disorders." (PMID 39338360, 2024).
soft tissue sarcoma (4 papers, 2012 to 2022). A malignant neoplasm arising from muscle tissue, adipose tissue, blood vessels, fibrous tissue, or other supportive tissues excluding the bones. "Therefore, we support the hypothesis that CCS belongs to the soft tissue sarcoma family and that the melanin synthesis is due to the specific action of the chimeric EWF/ATF1 protein via MITF activation." (PMID 22693489, 2012).
translocation renal cell carcinoma (4 papers, 2018 to 2023). "Translocation renal cell carcinoma (tRCC) is characterized by gene fusions involving two members of the Microphthalmia-associated transcription factor (MiTF) family: TFE3 and TFEB located on Xp11.2 and 6p21.1 respectively." (PMID 30987368, 2019). "Here we report a rare case of a 6-year-old male patient with MiT family translocation renal cell carcinoma (MiTF tRCC) where the patient developed retroperitoneal metastasis." (PMID 37528880, 2023).
bladder cancer (3 papers, 2022 to 2024). "Furthermore, a recent study showed that CCDC183-AS1 is involved in bladder cancer (BC) progression via an MITF/CCDC183-AS1/miR-4731-5p/TCF7L2 signaling axis, in which TCF7L2 was identified as an essential gene in the modulation of aerobic glycolysis (the Warburg effect)." (PMID 38254754, 2024).
COVID-19 (3 papers, 2021 to 2024). A disease caused by infection with severe acute respiratory syndrome coronavirus 2. "In agreement with previous studies, we also highlighted the elevation of ATF3, CEBPB, FOSL2, and MITF with COVID-19 severity." (PMID 39712003, 2024). "We identified macrophage-related functions (xenobiotic metabolism pathway and binding of MITF) that contribute more to the severe COVID-19 symptoms." (PMID 33923155, 2021). "MITF was also discovered as a potential indicator of the COVID-19 severity." (PMID 36230912, 2022).
dysplastic nevi (3 papers, 2020 to 2025). "As a marker of melanocytic differentiation, MITF is also expressed in benign melanocytic nevi, with studies reporting up to 83% of cases as positive, with similar results for Spitz nevi and dysplastic nevi." (PMID 40507250, 2025).
glioma (3 papers, 2013 to 2025). A benign or malignant brain and spinal cord tumor that arises from glial cells (astrocytes, oligodendrocytes, ependymal cells). "Importantly, six of them, except for RET and MITF, are involved in the DNA damage repair (DDR) pathway, indicating the importance of genomic instability in glioma genesis." (PMID 34885201, 2021).
lung adenocarcinoma (3 papers, 2020 to 2024). A carcinoma that arises from the lung and is characterized by the presence of malignant glandular epithelial cells. "The transcriptional landscape of MITF regulation in lung adenocarcinoma was evaluated and was associated with inflammation, development, cell cycle and WNT signaling pathways, which is consistent with previous studies." (PMID 33293474, 2020). "The results demonstrated an inverse association of MITF in lung adenocarcinoma." (PMID 33293474, 2020). "Studies have shown that in lung adenocarcinoma, CPT1B is subjected to direct transcriptional repression by the transcription factor MITF, and its high expression is able to facilitate stemness in lung adenocarcinoma cells by activating FAO." (PMID 39596847, 2024). "Given the existent transcripts of various MITF isoforms, the expression of different MITF isoforms in CL1-0 lung adenocarcinoma cells was measured." (PMID 33293474, 2020). "Whole transcriptome profiling of the landscape of MITF regulation in lung adenocarcinoma indicates that MITF is involved in cell development, cell cycle, inflammation and WNT signaling pathways." (PMID 33293474, 2020). "Strikingly, MITF has significantly inverse correlations with the expression of its downstream genes in lung adenocarcinoma." (PMID 33293474, 2020). "We manipulated MITF expression in lung adenocarcinoma cell lines and measured cell invasion and migration activities." (PMID 33293474, 2020). "Silencing MITF promotes tumor cell migration, invasion and colony formation in lung adenocarcinoma cells." (PMID 33293474, 2020). "Taken together, the results indicated that MITF suppressed both cell migration and invasion in lung adenocarcinoma cells." (PMID 33293474, 2020). "We found that MITF is dominantly expressed in the low-invasive CL1-0 lung adenocarcinoma cells and paired adjacent normal lung tissues." (PMID 33293474, 2020). "The rheostat model of MITF in lung adenocarcinoma is paradoxical, but the reciprocal regulation between MITF and WNT signaling matters." (PMID 33293474, 2020). "Further investigation is needed to elucidate the “rheostat model” of MITF in lung adenocarcinoma, and which transcriptional partners or modifications for MITF to shift its role in the progression of different malignancies." (PMID 33293474, 2020). "After depletion of MITF expression in lung adenocarcinoma, cell proliferation was unaltered but tumorigenesis and metastases increased, although cell cycle and proliferation were enriched pathways." (PMID 33293474, 2020). "The results showed that MITF expression was significantly associated with OS and progression-free survival (PFS) in lung adenocarcinoma (p-value 0.047 was for OS and 0.034 for PFS, log-rank test)." (PMID 33293474, 2020). "We further identified several targets of MITF in lung adenocarcinoma and clarified their effects on cancer progression by utilizing in vitro and in silico analyses." (PMID 33293474, 2020). "The role of MITF in angiogenesis has been less investigated in lung adenocarcinoma." (PMID 33293474, 2020). "Accordingly, MITF-mediated increase in angiogenesis in lung adenocarcinoma may be relevant to inhibition of both tumor growth and metastasis." (PMID 33293474, 2020). "We showed that MITF binds to the promoter of PTGR1 and downregulates PTGR1 expression in lung adenocarcinoma." (PMID 33293474, 2020). "However, NRF2 also affected COX2 expression in the lung adenocarcinoma cell line A549, which does not express MITF, indicating that the NRF2-dependent COX2 induction is not restricted to MITF-expressing cells and is therefore regulated, at least in part, by another mechanism." (PMID 32978520, 2020).
mesenchymal tumors (3 papers, 2016 to 2024). "A recent study found that reconstitution/recombination of MITF restored KIT expression levels in SH3BP2-silenced cells and restored cell viability in mesenchymal tumors, while also reducing MITF and ETV1 expressions." (PMID 38414063, 2024).
myocardial infarction (3 papers, 2020 to 2023). Gross necrosis of the myocardium, as a result of interruption of the blood supply to the area, as in coronary thrombosis. "Although high levels of MITF have been observed in cardiomyocytes and the heart, the role of MITF after myocardial infarction (MI) remains unclear." (PMID 32104183, 2020).
nevus (3 papers, 2021 to 2023). Nevus (or naevus, plural nevi or naevi, from nævus, Latin for "birthmark") is the medical term for sharply circumscribed[1] and chronic lesions of the skin or mucosa. "Strong GREB1 or MITF staining (score 3) was observed in 12/20 (60.0%) benign nevus samples." (PMID 37658191, 2023).
ocular albinism (3 papers, 2016 to 2021). Albinism affecting the eye in which pigment of the hair and skin is normal or only slightly diluted. "WS types 2A and 2 with ocular albinism (WS2-OA) both result from pathogenic variants in the microphthalmia-associated transcription factor gene (MITF), and present with SNHI and pigment disorders." (PMID 33396879, 2020). "In addition, some studies found that WS type 2 in conjunction with ocular albinism (OA) may result from a digenic mutation mechanism including both a MITF mutation and the TYR(R402Q) hypomorphic allele or TYRP mutation." (PMID 33506017, 2021).
paraganglioma (3 papers, 2008 to 2022). A benign or malignant neoplasm arising from paraganglia located along the sympathetic or parasympathetic nerves. "The tumor cells of paraganglioma are usually negative for melanocytic markers, such as Melan-A, HMB-45, and MITF." (PMID 18638402, 2008).
renal tumor (3 papers, 2011 to 2021). "Together, these data suggest that MITF upregulation is an important driver for kidney tumor formation." (PMID 22039523, 2011).
triple-negative breast carcinoma (3 papers, 2019 to 2025). An invasive breast carcinoma which is negative for expression of estrogen receptor (ER), progesterone receptor (PR), and human epidermal growth factor receptor 2 (HER2). "In addition, our results pointed out that the inhibition of Mcl-1 and MITF activity could be considered a target in triple-negative breast cancer treatment." (PMID 36045272, 2022). "Similarly, Akt2 is associated with proliferation, and phosphorylation at that particular site with activation, MITF promotes cell proliferation and invasion through the yes-associated protein 1 (YAP) signaling, a molecule associated with negative prognosis in triple-negative breast cancer." (PMID 41149583, 2025).
allergic disease (2 papers, 2019 to 2021). An immune response that occurs following re-exposure to an innocuous antigen, and that requires the presence of existing antibodies against that antigen. "Apart from its canonical mechanism, the p-LysRS-Ap4A-regulated MITF pathway is involved not only in allergic disease but also in cancer metastasis." (PMID 34070694, 2021).
Alzheimer disease (2 papers, 2024 to 2026). A progressive, neurodegenerative disease characterized by loss of function and death of nerve cells in several areas of the brain leading to loss of cognitive function such as memory and language. "Subcluster 2 expressed high levels of white matter associated genes (NRP1, MERTK, and NCKAP5) while subcluster 3 displayed a disease‐associated signature (STARD13, MITF, GPNMB, and DPYD) previously observed in Alzheimer's disease (AD) and Multiple Sclerosis (MS)." (PMID 41283828, 2026).
Anophthalmia (2 papers, 2012 to 2023). Absence of the globe or eyeball. "Disruption of MITF causes anophthalmia, hypopigmentation, and bilateral HL in mutant pigs, which mimics the phenotype of human WS2A, suggesting the potential of MITF−/− pigs for modeling human WS2A." (PMID 37210555, 2023).
atherosclerosis (2 papers, 2022 to 2024). A disease characterized by the build-up of fatty material and calcium deposition in the arterial wall resulting in partial or complete occlusion of the arterial lumen. "MITF regulate lysosomal biogenesis and function, and lysosomal dysfunction in macrophages has been reported as a risk of atherosclerosis development." (PMID 36513974, 2022). "At rs6772383, the risk T allele disrupts a TEAD1-binding site and is associated with decreased MITF expression in GTEx whole blood eQTL data, indicating that MITF expression is protective against atherosclerosis." (PMID 38747151, 2024).
Autoimmunity (2 papers, 2010 to 2024). The occurrence of an immune reaction against the organism's own cells or tissues. "Therefore, the upregulation of miR-96-182-83 in lupus lymphocytes may cause the decrease of Foxo1/3a and/or MITF, which in turn leads to the hyperactivation of B and T lymphocytes, immune tolerance breakdown and development of autoimmunity." (PMID 21170274, 2010). "Moreover, inactivation of MITF in mice induced spontaneous B cell activation and autoantibody production by suppressing interferon regulatory transcription factor (IRF)-4, which suggested a role of MITF in maintaining B cell immune tolerance and prevention of autoimmunity." (PMID 21170274, 2010).
breast tumor (2 papers, 2016 to 2019). "To validate PSIONIC-derived prognostic TFs, we perform immunohistochemical analyses in 31 uterine serous tumors for ETV6 and 45 basal breast tumors for MITF and confirm that the corresponding protein expression patterns are also significantly associated with prognosis." (PMID 31554806, 2019).
choroidal melanoma (2 papers, 2012 to 2016). Malignant tumor of melanocytes of the choroid. "Moreover, miRNA-146a is a target of MITF (Microphthalmia-associated Transcription Factor), a protooncogenic transcription factor acting as a master regulator of melanocyte development, function and survival; it also may be implicated in choroidal melanoma pigmentation and proliferation." (PMID 27895580, 2016). "Concordant with these findings, MITF in choroidal melanoma behaves as an oncogenic factor that is suppressed by miR-182 as demonstrated in this study, as well as by miR-137 in our previous report." (PMID 22848417, 2012).
chromophobe renal cell carcinoma (2 papers, 2023 to 2024). Chromophobe renal cell carcinoma is a rare subtype of renal cell carcinoma, originating from the intercalating cells of the collecting ducts and macroscopically manifesting as a well-circumscribed, highly lobulated, solid tumor that is usually diagnosed at an early stage. "In the TCGA chromophobe renal cell carcinoma dataset, originating also from distal tubules, TFCP2L1 and MITF expression correlated with that of CDH1." (PMID 37236926, 2023).
epithelial ovarian cancer (2 papers, 2017 to 2020). "However, there have been reports of inhibition of cancer metastasis, including in vivo, using MITF inhibitor, MCAM antibodies, and miRNA targeting MCAM; it is hoped that inhibition of the MITF/MCAM axis will inhibit metastasis of ovarian cancer." (PMID 33371469, 2020). "There have been no reports thus far on whether MITF contributes to cell migration and invasion in gynecological tumors, including ovarian cancer." (PMID 33371469, 2020).
epithelioid melanoma (2 papers, 2025). "While MiTF does not distinguish between benign and malignant melanocytic lesions, it remains a highly sensitive and specific histopathological marker for epithelioid melanoma in invasive neoplasms of unknown origin." (PMID 40509563, 2025).
heart failure (2 papers, 2023 to 2024). Inability of the heart to pump blood at an adequate rate to meet tissue metabolic requirements. "These core TFs include MITF (TF for aging DEGs in macrophage, fibroblast, and pericyte), a gene linking to the hypertrophic response, and AR (TF for aging DEGs in CM, macrophage, and fibroblast), a key molecular target to treat heart failure." (PMID 37084237, 2023).
Lynch syndrome (2 papers, 2022 to 2024). An autosomal dominant hereditary neoplastic syndrome characterized by the development of colorectal carcinoma and a high risk of developing endometrial carcinoma, gastric carcinoma, ovarian carcinoma, renal pelvis carcinoma, and small intestinal carcinoma. "Of 20 patientsinitially referred for Lynch syndrome, 3 had PV/LPVs on retesting, and noneultimately had this condition (CHEK2, MITF, MUTYH heterozygote,n = 1 each)." (PMID 34545504, 2022).
Lysosomal Storage Disorders (2 papers, 2022 to 2024). "Another group of diseases in which TFEB and the other transcription factors of the MiTF/TFE family seem to play an important role are lysosomal storage disorders (LSDs)." (PMID 35665902, 2022). "TFEB is a member of the MiTF/TFE family of basic helix-loop-helix leucine zipper transcription factors, linked to a range of conditions including neurodegenerative diseases, metabolic disorders, obesity, tumors, and lysosomal storage diseases." (PMID 38664707, 2024).
malignant soft tissue tumors (2 papers, 2024 to 2025). "ACTIN::MITF- and MITF::CREM-rearranged tumors are categorized as melanocytomas in the melanocytic tumors chapter while neoplasms with CRTC1::TRIM11 fusions are classified as malignant soft tissue tumors with uncertain differentiation." (PMID 39264472, 2024).
mast cell disease (2 papers, 2007 to 2023). "Others have shown that mast cell tryptase and MiTF are highly sensitive and specific markers for mast cell disease." (PMID 17705868, 2007). "Altogether, our data show that MITF and MITF-dependent targets may be therapeutic to target mast cell release abilities and survival in KIT oncogenic mast cell diseases." (PMID 36834926, 2023).
medulloblastoma (2 papers, 2014 to 2019). A malignant, invasive embryonal neoplasm arising from the cerebellum. "To determine whether the MITF->PGC-1 axis may be involved in the increased expression of respiratory chain genes in human SHH-MB, we checked the expression of genes encoding these proteins (MITF, PPARGC1A, and PPARGC1B) in medulloblastoma transcriptomic datasets." (PMID 30841515, 2019). "In contrast, the pre-rod-determination gene, MITF, and cone cell markers normally expressed after lineage commitment to cone cells, were not expressed in Group 3 medulloblastoma." (PMID 25412507, 2014).
nodular melanomas (2 papers, 2020 to 2021). "Nodular melanoma was more common in MITF+ patients (32% compared to 19% in MITF−)." (PMID 32054529, 2020).
osteoporosis (2 papers, 2019 to 2023). A condition of reduced bone mass, with decreased cortical thickness and a decrease in the number and size of the trabeculae of cancellous bone (but normal chemical composition), resulting in increased fracture incidence. "These genes were selected as variables to construct a molecular risk model for predicting osteoporosis (risk score = Exp (CTNNB1) × (−1.167227) + Exp (MITF) × (−5.192496) + Exp (TNFSF11) × (12.019122))." (PMID 37893075, 2023). "TNFSF11 was significantly upregulated (p = 0.001), whereas CTNNB1 (p = 0.001) and MITF (p = 0.017) were significantly downregulated, in the osteoporosis group." (PMID 37893075, 2023). "Based on the osteoclast-regulatory genes (CTNNB1, MITF, and TNFSF11) in the risk model, we used the R package “ConsensusClusterPlus” to cluster the osteoporosis patients." (PMID 37893075, 2023). "CTNNB1 and MITF are protective factors, whereas TNFSF11 is a risk factor for osteoporosis." (PMID 37893075, 2023). "In this study, we detected three key genes, CTNNB1, MITF, and TNFSF11, using microarray data for osteoporosis." (PMID 37893075, 2023). "In conclusion, CTNNB1, MITF, and TNFSF11 were identified as three key genes involved in the occurrence and development of osteoporosis." (PMID 37893075, 2023). "The key roles of these three genes in osteoporosis were verified using multivariate logistic regression, with CTNNB1 (OR = 3.501 × 10−7, p = 0.016) and MITF (OR = 2.475 × 10−14, p = 0.002) as protective factors and TNFSF11 (OR = 9.245 × 1022, p = 0.003) as a risk factor." (PMID 37893075, 2023).
osteosarcoma (2 papers, 2019 to 2020). A usually aggressive malignant bone-forming mesenchymal neoplasm, predominantly affecting adolescents and young adults. "We also verified the functionality of the HA-MITF protein by transducing an established osteosarcoma cell line, U2OS, known to be available for MITF-induced tyrosinase activation." (PMID 32605315, 2020).